AKR1C3 (aldo-keto reductase family 1 member C3)
Diseases named in the same sentence as AKR1C3 in open-access papers (continued):
Sharing a sentence is not in itself a finding about the gene and the disease.
breast tumors (1 paper, 2013). "We demonstrated positive and significant correlations between BRCA1, ERα, PR, aromatase, and AKR1C3 mRNA expression in various subsets of breast tumors." (PMID 24223121, 2013).
Cirrhosis (1 paper, 2022). A chronic disorder of the liver in which liver tissue becomes scarred and is partially replaced by regenerative nodules and fibrotic tissue resulting in loss of liver function. "We use the bioinformatical analysis to verify that AKR1C3, NQO1, TEK, and TPX2 have good diagnostic performance in patients with cirrhosis." (PMID 36686655, 2022). "The AUCs of expression of AKR1C3, NQO1, TEK, and TPX2 between cirrhosis and HCC were .9.74.77, and .89, proving that the four target genes have predictive value." (PMID 36686655, 2022).
diabetes (1 paper, 2020). "We observed that the gene expression levels of AKR1C1 and C2 had increased significantly and that the AKR1C3 mRNA level tended to be higher in the prostate tissue of patients with T2D than in samples of patients without diabetes." (PMID 32932589, 2020). "The expression level of AKR1C3 tended to be higher (p = 0.0557) in the PCa T2D group than in samples from patients without diabetes." (PMID 32932589, 2020).
diabetic neuropathy (1 paper, 2024). A chronic, pathological complication associated with diabetes mellitus, where nerve damages are incurred due to diabetic microvascular injury involving small blood vessels that supply these nerves, resulting in peripheral and/or autonomic nerve dysfunction. "Although the potency for inhibition of AKR1B1 is higher, therapeutic plasma concentrations of ranirestat, which is currently under development for the treatment of diabetic neuropathy are in the micromolar range and might, therefore, be high enough to efficaciously inhibit AKR1C3." (PMID 38175295, 2024).
Dysmenorrhea (1 paper, 2025). Pain during menstruation that interferes with daily activities. "However, the scientific literature has highlighted the role of the human aldose reductase enzymes (as AKR1C3) in the synthesis of PGF2α in the endometrium, especially in inflammatory conditions such as dysmenorrhea." (PMID 41301696, 2025).
endometrioid endometrial carcinoma (1 paper, 2020). "However, to better understand the roles of AKR1C3 in endometrioid endometrial carcinoma and in HGSC, other functions of this enzyme also need to be taken into account, which certainly warrants further studies." (PMID 33352741, 2020). "In endometrioid endometrial carcinoma, high AKR1C3 IHC expression correlated with better overall survival (hazard ratio, 0.19; 95% confidence interval, 0.06−0.65, p = 0.008) and with disease-free survival (hazard ratio, 0.328; 95% confidence interval, 0.12–0.88, p = 0.027)." (PMID 33352741, 2020).
Hyperglycemia (1 paper, 2020). An increased concentration of glucose in the blood. "Hyperglycemia was indeed found to induce the mRNA levels of AKR1C1, AKR1C2, and AKR1C3." (PMID 32932589, 2020).
influenza (1 paper, 2019). An acute viral infection of the respiratory tract, occurring in isolated cases, in epidemics, or in pandemics; it is caused by serologically different strains of viruses (influenzaviruses) designated A, B, and C, has a 3-day incubation period, and usually lasts for 3 to 10 days. "The top five genes of each of the two clusters (NK cell activity; NK and T‐cell activity) that were most closely correlated with influenza antibody titers had seven genes (SPON2, AKR1C3, PRF1, FCRL6, GZMA, CSTK, NKG7) which belong to the aging signature genes of IL‐7Rαlow EM CD8+ T cells." (PMID 31044512, 2019).
keloid (1 paper, 2024). An irregularly shaped, elevated mark on the skin caused by deposits of excessive amounts of collagen during wound healing. "As shown in, at the protein level, the expression of PLIN2 and AKR1C3 was significantly increased in keloid samples compared to normal samples, whereas the expression of SOCS2, SLC38A1, and SNCA was significantly decreased." (PMID 39834787, 2024). "In summary, we identified AKR1C3, PLIN2, SOCS2, SLC38A1, and SNCA as characteristic genes associated with ferroptosis in keloids through comprehensive transcriptomic data analysis." (PMID 39834787, 2024). "Additionally, as depicted in, at the mRNA level, there was also a significant increase in the expression of PLIN2 and AKR1C3 in keloid samples, and a significant decrease in the expression of SOCS2, SLC38A1, and SNCA." (PMID 39834787, 2024). "The upregulation of AKR1C3 in keloids may contribute to scar formation by affecting cell proliferation and extracellular matrix component deposition." (PMID 39834787, 2024). "In summary, the upregulation of AKR1C3 and PLIN2 in keloids may inhibit ferroptosis by affecting oxidative stress, as well as lipid metabolism and storage, thereby promoting cell proliferation and fibrosis, which further contributes to scar tissue formation." (PMID 39834787, 2024).
keratoconus (1 paper, 2023). A degenerative, structural disorder of the eye, characterized by a cone-shaped protrusion of the cornea. "In the present study, AKR1C3 was found to be responsible for the synthesis of miR-184, and the expression of AKR1C3 was decreased in keratoconus." (PMID 37626095, 2023). "We overlaid these 4 modules with FRGs and found that 8 FRGs (LCE2C, NOS2, AKR1C3, CAV1, MMD, LINC00618, SNCA, SLC7A11) were closely related to the disease state of keratoconus." (PMID 37626095, 2023).
laryngeal carcinoma (1 paper, 2013). Carcinoma that arises from the laryngeal epithelium. "In conclusion, we identified a novel molecular mechanism underlying a first case of HPV6-associated laryngeal carcinoma in juvenile-onset RRP, i.e. that HPV6 integration in the AKR1C3 gene resulted in loss of its expression." (PMID 23437342, 2013).
laryngeal papilloma (1 paper, 2013). "Our western blot and immunohistochemical results show that the AKR1C3 protein is also highly expressed in the laryngeal papilloma, but is downregulated in the carcinoma." (PMID 23437342, 2013).
mastocytosis (1 paper, 2017). A clonal myeloproliferative neoplasm characterized by the proliferation and accumulation of neoplastic mast cells in one or multiple organs or organ systems. "The highly significant repression and near complete silencing of AKR1C3 implies an adaptive response to the mastocytosis induced by diclofenac treatment." (PMID 29296203, 2017).
multiple myeloma (1 paper, 2025). "YY1 upregulates AKR1C3 and the hedgehog axis to enhance lenalidomide (LEN) resistance in multiple myeloma cells." (PMID 40867514, 2025). "In multiple myeloma, YY1 promotes AKR1C3 expression and activates hedgehog signaling to promote glycolytic activity and lenalidomide resistance." (PMID 40867514, 2025).
myelodysplastic syndrome (1 paper, 2012). A clonal hematopoietic disorder characterized by dysplasia and ineffective hematopoiesis in one or more of the hematopoietic cell lines. "In this regard, Murray and co-workers have used a combination of bezafibrate (to agonise PPARα) and medroxyprogesterone acetate (to inhibit AKR1C3) to treat a small number of elderly patients with myelodysplastic syndrome and AML." (PMID 23213553, 2012).
oral carcinoma (1 paper, 2017). "Cigarette smoke has been shown to induce cytochrome P450 (CYP1A1, CYP1B1) and aldo-keto reductase (AKR1C1, AKR1C3, AKR1B10) genes in oral dysplasia and primary oral carcinoma cell lines." (PMID 28467356, 2017).
oropharyngeal cancer (1 paper, 2023). Carcinoma, predominantly squamous cell, arising from the epithelial cells of the oropharynx. "Aldo-keto reductase family 1 member C3 (AKR1C3) has been associated with poor prognosis in patients with oropharyngeal cancer, especially in HPV-positive patients." (PMID 37705968, 2023).
oropharyngeal squamous cell carcinoma (1 paper, 2022). "According to a previous clinical study, upregulation of AKR1C3 is an indicator of poor prognosis in HPV16-associated and HPV-negative oropharyngeal squamous cell carcinoma (OPSCC)." (PMID 35646665, 2022).
osteoarthritis (1 paper, 2022). A noninflammatory degenerative joint disease occurring chiefly in older persons, characterized by degeneration of the articular cartilage, hypertrophy of bone at the margins and changes in the synovial membrane. "Taken together, our findings suggest that JGC treats synovitis in osteoarthritis by inhibiting AKR1C3." (PMID 36505054, 2022).
Parkinson disease (1 paper, 2025). A progressive degenerative disorder of the central nervous system characterized by loss of dopamine producing neurons in the substantia nigra and the presence of Lewy bodies in the substantia nigra and locus coeruleus. "Again, it regulates the Wnt/β‐catenin signaling pathway by suppressing AKR1C3 and α‐synuclein accumulation in 6‐OHDA‐induced Parkinson's disease (PD) in C57BL/6 mice models." (PMID 40783911, 2025).
preeclampsia (1 paper, 2025). Preeclampsia is a hypertensive disorder of pregnancy that is characterized by new-onset hypertension with proteinuria presenting after 20 weeks of gestation, and depending on mild or severe forms may initially present with severe headache, visual disturbances, and hyperreflexia. "In nonneoplastic diseases, increasing the expression of AKR1C3 in the kidneys of rats with preeclampsia could reduce the production of ROS in renal tissue, thereby exerting a therapeutic effect on preeclampsia." (PMID 40055914, 2025).
primary adrenal insufficiency (1 paper, 2021). A hormonal disorder that occurs when the adrenal glands fail to release adequate amounts of glucocorticoids (cortisol), mineralocorticoids (aldosterone, 11-deoxycorticosterone), and androgens (dehydroepiandrosterone) to meet physiologic needs, despite release of ACTH from the pituitary. "This is catalyzed by AKR1C3, which is predominantly expressed in NK cells, potentially linking adrenal 11-oxygenated androgen deficiency to the reduced NK cell cytotoxicity in primary adrenal insufficiency." (PMID 33444228, 2021).
prostate adenocarcinoma (1 paper, 2010). "Elevated expression of AKR1C3 has been identified and confirmed in some cases of localized and advanced prostate adenocarcinoma." (PMID 21134280, 2010). "The differences in AKR1C3 immunoreactivity obtained from sections prepared from an individual patient and tissue arrays might result from the uneven distribution of AKR1C3 in prostate adenocarcinoma." (PMID 21134280, 2010).
rectal cancer (1 paper, 2015). A primary or metastatic malignant neoplasm that affects the rectum. "In the present de novo meta-analysis study, we found three genes: CXCL10, IDO1 and AKR1C3 associated to chemo-resistance in rectal cancer patients." (PMID 26359356, 2015). "Drugs traditionally used in the adjuvant treatment of rectal cancer were reported in the network dependencies: capecitabine, 5-fluorouracil (both targeting AKR1C3), irinotecan and oxaliplatin and." (PMID 26359356, 2015).
stomach adenocarcinoma (1 paper, 2022). "Additionally, the survival analysis data obtained from the online cBioPortal were used to evaluate the prognostic significance of AKR1C1 and AKR1C3 mRNA expression levels in stomach adenocarcinoma tissue samples obtained from The Cancer Genomic Atlas (TCGA) Pan-Cancer Atlas data." (PMID 36292923, 2022).
thyroid cancer (1 paper, 2022). "In previous studies, BID, FBXW7, and GPX4 had already been found to be significant in thyroid cancer, whereas the role of AKR1C3 and MAP3K5 in the development and progression of thyroid cancer has not yet been reported." (PMID 35741758, 2022). "Knocking down AKR1C3 enhances thyroid cancer cell proliferation, invasion, and migration abilities." (PMID 35741758, 2022). "In addition, we discovered that AKR1C3 is a facilitating factor in thyroid cancer progression." (PMID 35741758, 2022). "AKR1C3, BID, FBXW7, GPX4, and MAP3K5 were independent prognosis signatures of thyroid cancer." (PMID 35741758, 2022). "Therefore, for further study, we chose AKR1C3, which has never been reported to function in the development and progression of thyroid cancer." (PMID 35741758, 2022).
tuberculosis (1 paper, 2025). A chronic, recurrent infection caused by the bacterium Mycobacterium tuberculosis. "Transcriptomic profiling identified five metabolically significant differentially expressed genes (FHIT, MAN1C1, SLC4C7, NT5E, AKR1C3; p < 0.05) that effectively distinguish between latent tuberculosis infection (LTBI) and active tuberculosis (TB)." (PMID 40524207, 2025).
tumor (85 papers, 2004 to 2025). "Consistently, loss of AKR1C3 synergized with sorafenib to inhibit tumor growth by inducing lipophagy." (PMID 36451864, 2022). "They reported that the tumor contained integration of low-risk HPV type 6 in the Aldo-Keto Reductase 1C3 (AKR1C3) gene, deletion of the corresponding chromosomal region 10p14–10p15.2, and loss of AKR1C3 protein expression." (PMID 34439243, 2021). "Unexpectedly, high levels of AKR1C3 were associated with a longer OS, although AKR1C3 protein expression has previously been linked with tumor progression." (PMID 34440208, 2021). "Based on this finding, it was hypothesized that the inhibition of xenograft tumor growth was caused by a reduced expression of AKR1C3." (PMID 36794010, 2023). "We found that the mRNA level of AKR1C3 was higher in EAC tumor tissues, and that high AKR1C3 expression might be associated with poor overall survival of EAC patients." (PMID 34065695, 2021). "Furthermore, 2.8% of tumor samples showed AKR1C3 mutations, including amplifications, deep deletions, and missense mutations; 2% of the samples also showed genetic alterations in the AKR1D1 gene." (PMID 33493134, 2021). "In contrast, increasing cdk4 dramatically increased these transcript levels, especially those encoding AKR1C3, an enzyme that converts estrone to 17β-estradiol, a change that could result in a pro-estrogenic state favoring tumor growth." (PMID 24848372, 2014). "Docking results showed that α-tocopherol has the highest binding energy with AKR1C3 (aldo-keto reductase family 1 member C3), indicating its potential to inhibit this enzyme and possibly affect the control of tumor cell growth." (PMID 40361686, 2025). "Our target gene, the Aldo-keto reductase family 1 member C3 (AKR1C3) gene, has been reported to be highly expressed in breast malignancies and is associated with tumor invasiveness, aggression, and resistance to chemotherapy." (PMID 40489436, 2025). "The expression of AKR1C3 in human tumor surgical samples exhibits heterogeneity across various cancer types." (PMID 38523637, 2024). "The complex formed by AKR1C3 and AR-V7 was found to be crucial for tumor growth in CRPC cells after ADT treatment, suppressing the protein degradation of both components." (PMID 38523637, 2024). "Chemical inhibition of AKR1C3, such as with the indomethacin inhibitor, has been shown to restore sensitivity to radiation in acquired tumor cells, highlighting AKR1C3 as a potential target for overcoming radioresistance." (PMID 38523637, 2024). "Immunostaining confirmed the substantial upregulation of AKR1C3 in tumor vs. normal human brain at the protein level." (PMID 39001492, 2024). "Elevated levels of AKR1C3 activate androgen receptor (AR) signaling pathway, contributing to tumor recurrence and imparting resistance to cancer therapies." (PMID 38523637, 2024). "This review aims to provide a comprehensive analysis of AKR1C3’s role in carcinoma development, its implications in therapeutic resistance, and recent advancements in the development of AKR1C3 inhibitors for tumor therapies." (PMID 38523637, 2024). "Inhibiting AKR1C3 has demonstrated potent efficacy in suppressing tumor progression and overcoming treatment resistance." (PMID 38523637, 2024). "The anthracycline induced the tumor apoptosis through reactive oxygen species (ROS) activation, while the malignant cells become drug-resistant by upregulating the AKR1C3 to reduce ROS activity." (PMID 38227591, 2024). "FOS, SERPINE1, AKR1C3, and FGF2 are the genes that potentially play important roles in HCC and are associated with tumor growth." (PMID 37057280, 2023). "High expression of AKR1C3 is associated with a worse prognosis in patients with HCC, and knockdown of AKR1C3 inhibits tumor cell proliferation, decreases cell viability, and inhibits tumorigenesis." (PMID 37057280, 2023). "In the 4 GEO datasets, AKR1C3 mRNA expression increased 2.76-fold in the tumor tissues on average (GEO database)." (PMID 38188684, 2023).